WNT7B (Wnt family member 7B)
Diseases named in the same sentence as WNT7B in open-access papers (continued):
Sharing a sentence is not in itself a finding about the gene and the disease.
tumor (continued). "WNT7B was recently shown to be significantly correlated with LUSC and OSCC development and was thought to be involved in promoting the ability of tumor cells to invade the surrounding area." (PMID 41184502, 2025). "WNT7B and WNT target genes are upregulated in CCA, and inhibition of canonical WNT signaling reduces CCA tumor burden in rodent models." (PMID 39636699, 2024). "Combined expression of WNT ligands (WNT3A, WNT4, WNT7B, WNT9A, WNT10A, WNT11) in BRCA patient tumours has a positive correlation (R = 0.27, p value = 0) with the combined expression of key EMT-inducing transcription factors SNAI1, SNAI2, ZEB1, ZEB2 and TWIST1." (PMID 38678032, 2024). "For instances, differentially methylated m6As in genes such as CENPF, WNT7B and NTSR1 between tumor and normal tissues were hypermethylated in S2 PDAC samples compared to S1 PDAC samples." (PMID 37816727, 2023). "Taken together, our findings showed that WNT7B and MMP1 are involved in oral inflammation and tumor progression." (PMID 35850748, 2022). "Especially, a panel of WNT components, including WNT5A, WNT7B, GPC1, and FZD6 or FZD7, shows tumor tissue-specific increment in CSCC, HNSC, LUSC, and BTCC." (PMID 35850748, 2022). "Conversely, WNT5A, WNT7B, WNT2, WNT7A, WNT10A and WNT3 were tumor-positive WNTs, which significantly increased in many carcinomas." (PMID 35850748, 2022). "Further analysis of the correlation between the WNT gene family and clinicopathological parameters of UCEC showed that the WNT1, WNT3, WNT7A, WNT7B, WNT8B, and WNT10A genes were expressed at significantly different levels at different tumor stages." (PMID 34565373, 2021). "A cohort of 98 OS patients analyzed by RNA-seq was analyzed for WNT7B and WNT9A expression in the tumor and four groups were generated according to the expression of the two genes around their respective means." (PMID 32686768, 2020). "Consistent with previous reports in PDAC organoids, WNT5A, WNT7A, WNT7B, and WNT10A mRNA were highly expressed in PDCLs, suggesting a tumor cell-intrinsic origin for these WNT ligands." (PMID 32402285, 2020). "(E) Wnt7b and Wnt10a expression in MEC (n = 3) and MEKO tumor cells (n = 3) is presented as the mean fragments per kilobase of exon model per million mapped fragments (FPKM) ± SEM." (PMID 29856313, 2018). "We cover fundamental molecular players in the tumor microenvironment including extra- (CCL2, CSF-1, CXCL12, IL-4, IL-13, semaphorins, WNT5A, and WNT7B) and intracellular signals." (PMID 28197019, 2017). "We found that WNT974 monotherapy modestly decreased Wnt7b but did not affect β-catenin levels in the tumor tissues." (PMID 40953263, 2025). "Our findings suggest that WNT2 and WNT7B act as potential oncogenic drivers, whereas WNT11 may serve as a tumor suppressor." (PMID 41044153, 2025). "We test mRNA expression of key genes affected by these methylation patterns and observe that the protein expression pattern of WNT7B demonstrates no steep changes at the tumor boundary, supporting their regulatory role." (PMID 41184502, 2025). "Similarly, exosome-mediated angiogenesis, involving molecules like Wnt7b mRNA, VEGFA, and miR-381-3p, supports tumor vascularization and progression." (PMID 41154440, 2025). "Additionally, pan-cancer analysis highlighted the tissue- and tumor-specific expression patterns of WNT2, WNT7B, and WNT11 across various cancers, in agreement with previous studies." (PMID 41044153, 2025). "Many in vitro and in vivo studies show that in different tumor types, such as colorectal, lung, breast, or hepatocellular cancer, specific WNTs, including WNT1, WNT2, WNT3A, WNT6, WNT8B, WNT7B, and WNT16B, can activate canonical Wnt signaling and support tumor proliferation." (PMID 36982422, 2023). "Another study in 37 patients with different types of CCA (9 iCCA and 28 pCCA) described higher levels of Wnt7b and Wnt10a ligands in tumor samples compared with matched non-tumor tissues." (PMID 37190050, 2023).
tumor (continued). "Moreover, WNT7B was demonstrated to contribute to the development of oral chronic inflammation and OSCC, partly due to promoting the invasion ability of tumor cells." (PMID 35850748, 2022). "Furthermore, the protein levels of Wnt7B and PCNA were declined, whereas the ratio of cleaved-caspase 3/total-caspase 3 was elevated in tumor tissues from the sh-irc_0082375 group." (PMID 34868669, 2021). "A large number of oncogenes as target genes of miR-505 in tumor cells, including TGF-α, HMGB1, FZD4, IGF1R, WNT7B, MAP3K3, NRCAM, and RUNX2, have been recognized as direct target genes of miR-505." (PMID 33520999, 2020). "On the other hand, the decreased levels of mRNAs encoding type I collagen, type IV collagen, laminin subunit gamma 2 and two proto oncogenes WNT7B and CTHRC1, suggest a complex and profound effect of the sera of patients with spontaneous tumour regression on the cancer cells." (PMID 27704726, 2017). "Worth to note, CNAs of 37 genes were exclusively found in G3 tumours such as WNT7B (4 gains), BAD (3 gains), WEGFB (3 gains) and HDAC2 (3 losses) in respect to 65 CNA genes exclusively presented in G1 tumours, such as GRB2 (5 losses) and FGF21, STAT3, CTNNA3 and DVL3 with 3 losses each." (PMID 28486536, 2017). "Interestingly, bulk RNA-Seq data revealed WNT7B upregulation in both KPTN tumors and organoids, where it functions as an essential niche factor for maintaining human pancreatic organoid cultures and supporting tumor growth." (PMID 41480763, 2026). "The rapid proliferation of tumor cells leads to tumor ischemia and hypoxia, which directly stimulates angiogenesis and promotes the secretion of cytokines such as matrix metalloproteinase-9 (MMP9), C-X-C motif chemokine ligand 12 (CXCL12) and Wnt7B by various cells, especially tumor cells." (PMID 35454769, 2022). "Results showed that the knockdown of WNT7B did not inhibit the proliferation of tumor cells." (PMID 35850748, 2022). "For example, activity changes in oncogenic pathways often modulate the tumor microenvironment, and we observed a strong correlation between promoter or enhancer methylation and target gene expression for the MAPK pathway (EGFR) and WNT-beta-catenin pathways (CTNNB1, WNT3A and WNT7B)." (PMID 34987166, 2022). "Unfortunately, graft experiments of the early passage tumour-derived cell lines in immunodeficient NSG mice did not result in tumour outgrowth as is often observed with primary tumours making it impossible to confirm the effects of WNT7b in this complementary in vivo setting." (PMID 30926782, 2019). "The analysis of the corresponding tumor and non-tumor samples also revealed upregulation of COMP, matrix proteins such as COL5A1, COL11A1, and FN1, and genes of the Wnt pathway (WNT7B, FZD10, SFRP2), while PLCB1, CAMK2B, PLCB4 and WIF1 are downregulated." (PMID 33227073, 2020). "However, we observed that optiCA1 overexpressing tumor cells, when compared with the controls, had not statistically changed expression profile of mRNAs (COL1A1, COL4A4, LAMC2, CTHRC1, and WNT7B)." (PMID 31963697, 2020).
cancer (53 papers, 2012 to 2026). A tumor composed of atypical neoplastic, often pleomorphic cells that invade other tissues. "MYC and WNT7B are implicated in the signaling related to the self-renewal and differentiation of cancer stem cells." (PMID 38670944, 2024). "Both genes encode proteins that are linked to cancer hallmarks—Epha1 is an ephrin receptor subfamily of the protein-tyrosine kinase family and Wnt7b is a WNT family member." (PMID 34398873, 2021). "To further illustrate these findings, we examined the cancer-associated gene WNT7B as an example." (PMID 41184502, 2025). "Specifically, cancers with SALL2 mutations displayed upregulated WNT7B and downregulated AXIN2." (PMID 40869218, 2025). "One of the most prominent DMRs in the final model was located near the WNT7B gene, which was hypermethylated in cancer patients (6% difference compared to controls)." (PMID 41155454, 2025). "This cancer cell subpopulation also showed statistically significant elevated expression of WNT7B, WNT7A, WNT10A and WNT4 besides the CSC markers, compared to the rest of the PDAC cells." (PMID 38678032, 2024). "Deletions in or near prominent cancer-associated genes (for example, ALK, LIN28B, PDGFD and WNT7B) were also detected." (PMID 37188965, 2023). "Our data annotated 17 WNTs and found that WNT2B, WNT10A, WNT5A and WNT7B showed a similar cancer-positive pattern, and WNT7B was the most significant one." (PMID 35850748, 2022). "At the same time, we also detected WNT7B expression in oral inflammation and carcinoma, and constructed stable WNT7B knockdown OSCC cell lines to study the effects of WNT7B on the cell migration and invasion ability." (PMID 35850748, 2022). "Wnt7b, an important member of the Wnt proteins family, have been reported highly-expressed in many malignant tumors, including BC." (PMID 33912460, 2021). "Of note, Wnt7b have been reported facilitate several cancers tumorigenesis via regulating canonical Wnt/β-catenin signaling." (PMID 33912460, 2021). "Cancer and proliferation-related genes such as Wnt7b, S100a14, and Erbb2, were downregulated by thermal ablation in directly-treated tumors (A-T) 1 week after ablation, and to a lesser extent, 24 h after mechanical HIFU (M-T) compared to control (NTC)." (PMID 33441763, 2021). "It was found that during the early progression of metastasis, the WNT7B signalling pathway is involved in the migration and invasion of cancer cells." (PMID 27704726, 2017). "In macrophages grown as co-culture with cancer cells expression of three ligands of Wnt pathway increased significantly: Wnt5b, Wnt7a and Wnt7b." (PMID 22353646, 2012). "The analysis also confirmed down-regulation of CCL2, IL18, and up-regulation of Wnt7b genes in macrophages grown under co-culture conditions with cancer cells." (PMID 22353646, 2012). "The top 20 up‐ and down‐regulated genes between malignant and mesothelial populations showed expected markers, such as PVRL4 or COL5A2, as well as genes that suggested a metabolically active cancer cell phenotype (WNT7B) and reactive mesothelial cells (MMP2 and LRP1) (upper heatmap)." (PMID 37691350, 2023). "PRDX6 may promote the occurrence and development of ICC by regulating Wnt7a/Mmp7 in cancer cells and Wnt7b/Ccnd2 in macrophages." (PMID 36209344, 2022). "Wnt7a is mainly expressed in cancer cells and Wnt7b is expressed in macrophages." (PMID 36209344, 2022). "It suggests that Wnt10 may be involved in the induction of tumors; while Wnt7b may be involved in the progression of cancer." (PMID 32140709, 2020). "The top twenty differentially expressed genes in pathways in cancer (PC) include the well-known oncogene NRAS, the inhibitor of apoptosis BIRC3/cIAP2, and WNT7B, a component of the WNT/β-catenin pathway." (PMID 41467516, 2026). "Investigation of the genetic alteration status of WNT2, WNT7B, and WNT11 in patients with BRCA across various cancer cohorts using cBioPortal has revealed notable insights." (PMID 41044153, 2025).
cancer (continued). "Both WNT2 and WNT7B showed elevated expression levels across individual cancer stages; in particular, WNT2 had higher expression at stage 1, whereas WNT7B had higher expression at stage 4 compared to normal tissues." (PMID 41044153, 2025). "To investigate the patterns of WNT2, WNT7B, and WNT11 expression in various cancer types, we used TIMER2.0, to explore the expression levels of WNT2, WNT7B, and WNT11 in 33 cancer types and matched normal pairs from the TCGA and GTEx databases." (PMID 41044153, 2025). "Among the WNT ligands, WNT7A, WNT7B and WNT10A have the highest expression in cancer cells, and the largest increase in expression in bulk PDACs compared to normal pancreatic tissue." (PMID 38678032, 2024). "We then analysed the expression of WNT ligands (WNT7B, WNT9A, WNT3A, WNT4) in RBL2-LOH cancer cell lines (HCC1500 and Cal-51) and in RBL2-wildtype cancers (MCF7 and T47D)." (PMID 38678032, 2024). "Consistently, we detected increased mRNA expression of WNT7B (P = 0.0003), as well as WNT10A (P = 0.0023) and WNT5A (P = 0.088), in most cancer samples." (PMID 35850748, 2022). "Conversely, the cancer cell–derived WNT7A, WNT7B, and WNT10A and stromal WNT3 and WNT9A were highly expressed in the squamous subtype." (PMID 35536676, 2022). "WNT ligands also changed expression levels in cancers, e.g. WNT3A, WNT5A and WNT7B were upregulated in cholangiocarcinoma." (PMID 35850748, 2022). "Therefore, we assumed that WNT7B may affect oral inflammation and cancer progression." (PMID 35850748, 2022). "Beyond this, the pathway in cancer revealed that most of the genes are relative to WNT pathway (WNT7B, WNT6, WNT10B, FZD6, FZD8, and LPAR5), and among these, WNT7B, WNT10B, FZD6, FZD8, and LPAR5 belonged to the classical WNT pathway." (PMID 34122668, 2021). "Some recent studies revealed that this downregulated miRNA was detected to have an essential effect on cancer cell proliferation, migration, invasion, metastasis, and angiogenesis through targeting multiple oncogenic genes HOXB5, WNT7B and LncRNA HAND2-AS1." (PMID 33910530, 2021). "This last group included genes involved in cell migration and ECM (e.g. RAB6B, FN1, VCAM1 or COL14A1) and genes of signalling pathways usually deregulated in cancer, such as Notch and Wnt signalling (JAG1 and WNT7B, respectively)." (PMID 34353313, 2021). "Surprisingly, both CA9 and WNT7B are downregulated in HCC, most so in stage-I, contrary to their role in other cancers." (PMID 31277598, 2019). "Our findings suggest that TQ modulates Wnt signaling by altering the expression of its core components (WNT7B and WNT6) and regulators (PDE2A and Sema3C), thereby potentially downregulating this oncogenic pathway and contributing to its anti-cancer mechanism in vitro." (PMID 39874307, 2025). "Our analysis revealed the strongest positive correlation between WNT7B, and genes co-expressed with 19 and 24 anti-cancer drugs, and a negative correlation with 6 and 4 drugs, respectively." (PMID 41044153, 2025). "In addition to human orthologs previously identified as playing key roles in OSCC, p63 signaling, and other cancers, namely, FAT2, K14, and PERP, we identified several novel regulators, including Cotl1, Bcam, Adipor2, and Wnt7b." (PMID 36672394, 2023). "We then explored by real-time qPCR the impact of miR-662 overexpression in MDA-MB-231 cells on expression levels of well-established stemness markers that are involved in embryogenesis and cancer –NOTCH1, WNT7b, ZEB1, TCF3, CTNNB1, CD44, CD24, SNAI2, OCT-04, c-MYC, EZH2–." (PMID 37443350, 2023). "While positive staining for WNT7B was observed obviously in the cytoplasm of the majority of malignant tissues, WNT5A, FZD7 and GPC1 signals were presented on both the cytoplasm and membrane of cancer cells." (PMID 35850748, 2022). "In our data, GLRX was considered to regulate the cancer stem cell phenotype via non-canonical Wnt signaling pathways associated with RhoA and ABCG2 via Wnt5a and Wnt7b." (PMID 34794402, 2021).
cancer (continued). "Wnt family member 7B (WNT7B; GO:1901701~cellular response to oxygen-containing compound in JNP vs Yorkshire pigs, ssc05205: proteoglycans in cancer in JNP vs Yorkshire pigs) is required for epithelial progenitor growth and is involved in the pancreatic development." (PMID 31480194, 2020). "For the purposes of the microarray data validation, we have selected 9 genes that may play the most important role in cancer cells-macrophages interactions: CCL2, CCL3, CD163, CSF1R, HIF1, Il-18, MMP9, VEGF-C, and Wnt7b." (PMID 22353646, 2012). "Furthermore, miR-662 overexpression in MDA-MB-231 cells substantially increased mRNA expression levels of stemness markers involved in embryogenesis and cancer, such as NOTCH1, WNT7b, ZEB1, TCF3, and SNAI2, reinforcing the notion that miR-662 expression enhanced stem-like properties of BC cells." (PMID 37443350, 2023). "Sequencing results showed that Wnt7a, Wnt7b, Fzd2, Mmp7 and Ccnd2 in the Wnt signaling pathway were downregulated after PRDX6 knockout, suggesting that this signaling pathway may be involved in the regulation of PRDX6's cancer-promoting effect." (PMID 36209344, 2022). "Of note, four of the cancer genes present in the network (MAP2K2, E2F1, FZD2, and WNT7B), although absent from our high-confident list of CIRBP targets, are enriched in CIRBP IPs." (PMID 33172965, 2021).
infection (3 papers, 2022 to 2024). The state of being infected such as from the introduction of a foreign agent such as serum, vaccine, antigenic substance or organism. "Moreover, RECK regulates MMP9 and exerts its effects primarily through suppression of WNT7A/WNT7B, but regulation of neither Wnt7a nor Wnt7b regulation was observed in our gene microarray dataset, and scRNA-Seq did not detect Wnt7a nor Wnt7b expression, before or after infection, in any ME cells." (PMID 36092940, 2022).
kidney disorder (1 paper, 2022). A disease involving the kidney. "The genes UPK3A, FBLN1, WNT7B, and CELSR1 have the strongest evidence of association with kidney disorders." (PMID 35741804, 2022). "Using association analysis, candidate gene prioritization based upon a set of known kidney-related genes and estimates of haploinsufficiency, we identified UPK3A, FBLN1, WNT7B, and CELSR1 as priority candidate genes for kidney disorders." (PMID 35741804, 2022). "The results from this study suggest that UPK3A, FBLN1, WNT7B, and CELSR1 are strong candidate genes for kidney disorders in PMS and merit functional studies." (PMID 35741804, 2022).
neurodegenerative disease (1 paper, 2022). A disorder of the central nervous system characterized by gradual and progressive loss of neural tissue and neurologic function. "WNT7B, a ligand of the Wnt signaling pathway, has been studied to demonstrate that dysregulation of the Wnt signaling pathway may be associated with synaptic failure and impaired cognitive function in neurodegenerative diseases." (PMID 34975305, 2022).
WNT7B also shares sentences with these, for which no sentence is quoted: adenocarcinoma (2 papers); colon carcinoma (2); lymph node metastasis (2); oesophageal cancer (2); oral squamous cell carcinoma (2); acute kidney injury (1); apical periodontitis (1); autism spectrum disorder (1); brain cancer (1); chondrosarcoma (1); cocaine use disorder (1); colorectal adenoma (1); diabetes (1); endometriosis (1); esophageal cancer (1); Hypertension (1); Infertility (1); kidney damage (1); leukemia (1); Macrocephaly (1); mucoepidermoid carcinoma (1); osteogenesis imperfecta (1); Peyronie disease (1); Phelan-McDermid syndrome (1); Pleural effusion (1); psychiatric disorder (1); skin cutaneous melanoma (1); soft tissue sarcoma (1); teratocarcinoma (1); thymoma (1).
A further 3 diseases each share a sentence with WNT7B in 1 paper.